CHIC1 (cysteine rich hydrophobic domain 1)
Synonyms: BRX
Tractability: Antibody: UniProt places it where antibodies can reach, with medium confidence; its Gene Ontology location is reachable by antibodies, with medium confidence. PROTAC: ubiquitination databases record sites on it.
Gene: Protein-coding gene on chromosome X (73,563,197 to 73,687,111, forward strand). Ensembl gene ENSG00000204116.
Subcellular location: Cell membrane; Cytoplasmic vesicle
Subcellular location (Human Protein Atlas): Nuclear speckles; Vesicles; Cytosol
Gene Ontology:
Cellular component: cytoplasmic vesicle; plasma membrane
Homologues: Orthologues: chimpanzee CHIC1 (100% identical), macaque CHIC1 (99% identical), pig CHIC1 (98% identical), rabbit CHIC1 (97% identical), rat Chic1 (96% identical), mouse Chic1 (95% identical), guinea pig CHIC1 (94% identical), dog CHIC1 (88% identical), zebrafish chic1 (69% identical), tropical clawed frog chic1 (68% identical), Drosophila melanogaster CG5938 (46% identical), Caenorhabditis elegans tag-266 (36% identical). Paralogues in human: CHIC2 (60% identical).
Diseases named in the same sentence as CHIC1 in open-access papers:
CHIC1 is named in the same sentence as 2 diseases in open-access papers, as found by Europe PMC text mining. Sharing a sentence is not in itself a finding about the gene and the disease. The quoted sentences say what the papers report.
leukaemia (1 paper, 2018). "However, CHIC1 and CHIC2 were both originally identified as Brain x-linked protein (Brx) and BrX-like translocated in leukaemia (BTL), respectively, and their roles in the regulation of nuclear hormone receptors and exocytosis have been described." (PMID 29297095, 2018).
CHIC1 also shares sentences with these, for which no sentence is quoted: tumor (1 paper).